PCSK9 (proprotein convertase subtilisin/kexin type 9)
Diseases named in the same sentence as PCSK9 in open-access papers (continued):
Sharing a sentence is not in itself a finding about the gene and the disease.
hyperlipidemia (continued). "Most patients suffering from cardiovascular disease or hyperlipidemia should use ezetimibe before PCSK9 inhibitors." (PMID 39176329, 2024). "For example, PCSK9 inhibitors, which have been used to treat hyperlipidemia, increase years of life." (PMID 38575325, 2024). "This is exemplified by the recent success story of GWAS discoveries leading to rapid development of monoclonal antibodies targeting proprotein convertase subtilisin/kexin type 9 (PCSK9) for hyperlipidemia and cardiovascular diseases." (PMID 38648183, 2024). "We also confirmed a causal relationship between APOB, PCSK9, and NCAN and hyperlipidemia in the external dataset." (PMID 39474612, 2024). "In response to this challenge, an inhibitor targeting proprotein convertase subtilisin-kexin type 9 (PCSK9) has been developed as a therapeutic intervention for hyperlipidemia." (PMID 39767636, 2024). "In a murine model exhibiting hyperlipidemia and elevated levels of PCSK9 expression, an observable augmentation in monocyte infiltration within the vascular wall was noted." (PMID 39767636, 2024). "Based on this network meta-analysis (NMA) results, evolocumab has emerged as a promising treatment option for patients with hyperlipidemia and muscle disorders compared to other PCSK9 inhibitors and inclisiran." (PMID 39040999, 2024). "Current treatment options for hyperlipidemia largely consist of statins, fibrates, ezetimibe, and PCSK9 inhibitors." (PMID 38919858, 2024). "Emerging evidence highlighting the link between tumors and hyperlipidemia further underscores the potential of PCSK9 inhibitors." (PMID 39324018, 2024). "In a mouse model of hyperlipidemia with high PCSK9 expression, there was an observed increase in monocyte infiltration within the vessel wall." (PMID 39767636, 2024). "The effects of lipid‐lowering drugs [including statins, ezetimibe, and proprotein convertase subtilisin/kexin type 9 (PCSK9) inhibitors] on hyperlipidaemia have been established." (PMID 39254080, 2024). "In summary, the discovery of the PCSK9 gene and related LOF mutations lays the foundation for new therapeutic strategies targeting PCSK9 for the treatment of hyperlipidemia and ASCVD." (PMID 38344397, 2024). "In control mouse strains, hyperlipidemia is rapidly induced by AAV-mediated increases in hepatic Pcsk9 expression and persists for at least one year." (PMID 37086367, 2023). "As previously reviewed, the expression of miR-27a, miR-140-5p, miR-191, miR-222, miR-224, miR-378a-3p, miR-140-5p, miR-483, and miR-520d-5p modulates pathogenesis of hyperlipidemia by targeting proprotein convertase subtilisin/kexin type 9 (PCSK9)." (PMID 36980601, 2023). "Carboxylesterase‐responsive motifs are introduced in the vehicle, endowing the delivery vehicle enzymatic responsiveness in hepatocyte and disrupt the target PCSK9 gene and achieve a potent therapeutic efficacy for hyperlipidemia." (PMID 37083231, 2023). "Proprotein convertase subtilisin kexin type 9 (PCSK9) has recently garnered significant attention as a target for increasing low-density lipoprotein cholesterol (LDL-C) levels in patients with hyperlipidemia." (PMID 38273837, 2023). "In a multivariable linear regression model, age, sex, BMI, and hyperlipidemia were independent predictors of plasma PCSK9 levels." (PMID 38094682, 2023).
hyperlipidemia (continued). "We also treated young and old C57BL/6 mice with AAV containing a modified Pcsk9 gene to acutely induce hyperlipidemia and assessed the same outcomes." (PMID 37086367, 2023). "Third, in combination with PCL, we utilized AAV-mediated upregulation of Pcsk9 and AD to acutely induce hyperlipidemia in young and old mice." (PMID 37086367, 2023). "In order to investigate the effect of PCSK9 inhibitors on mTOR inhibitors-induced hyperlipidemia, the liver of the mice was collected for analysis on the twelfth day after the first drug treatment." (PMID 37896137, 2023). "PCSK9 mAb therapy significantly reduced hepatic steatosis, liver inflammation, and fibrosis in patients with severe hyperlipidemia." (PMID 37466835, 2023). "In patients with hyperlipidemia, PCSK9 induces the expression of C-C chemokine receptor type 2 (CCR2) on the surface of monocytes and enhances their migration ability." (PMID 36970356, 2023). "In phase III trials of bococizumab, also an antibody against PCSK9 and used for the treatment of hyperlipidemia, high levels of anti-bococizumab antibodies developed in patients, reducing overall drug efficacy." (PMID 37764213, 2023). "We additionally induced hyperlipidemia in young and old C57BL/6 mice by adeno-associated virus mediated upregulation of LDL receptor regulator, Pcsk9, and 5 weeks of AD." (PMID 37086367, 2023). "PCSK9 inhibitors, Evolocumab and Alirocumab, have been approved for the clinical treatment of hyperlipidemia." (PMID 36902778, 2023). "For primary hyperlipidemia due to heterologous familial hypercholesterolemia (HeFH) and HoFH, statins and PCSK9 inhibitors (that function by increasing the number of LDL receptors) are less effective in treatment due to the absence of LDL receptor expression." (PMID 37764213, 2023). "In conclusion, the mechanism of PCSK9 inhibitors on Rapamycin-induced hyperlipidemia needs to be further studied." (PMID 37896137, 2023). "Over the past few years, PCSK9 inhibitors have become a new hot spot for drug development in hyperlipidemia and atherosclerotic heart disease." (PMID 37896137, 2023). "While statins are the mainstay of hyperlipidemia treatment, there are alternative medication options, such as ezetimibe and PCSK9 inhibitors, for those who cannot tolerate statins." (PMID 35130899, 2022). "The database search included PubMed and Cochrane using the following keywords: acute ischemic stroke, stroke, PCSK-9 inhibitors, secondary and primary prevention, alirocumab, evolocumab, bococizumab, inclisiran, hyperlipidemia." (PMID 36142135, 2022). "Although PCSK9 (proprotein convertase subtilisin/kexin type 9) inhibitors (monoclonal antibody) bring a new era on hyperlipidemia treatment, however, low safety profile and high cost limit its application." (PMID 35757107, 2022). "While PCSK9 inhibitors show significant potential in their ability to treat hyperlipidemia in a safe and efficacious manner, it should be mentioned that the monthly cost of these drugs is currently prohibitive." (PMID 36554779, 2022). "As such, many patients require adjunct therapies to properly control hyperlipidemia, including niacin, bile acid sequestrants, fibric acids, and cholesterol absorption inhibitor ezetimibe, as well as the recently approved class PCSK9 inhibitors." (PMID 36498935, 2022). "By reducing LDL-C content, inhibiting PA and thrombosis, and reducing the production of inflammatory substances, PCSK9 can treat hyperlipidemia, As, lipoprotein(a), venous thromboembolism (VTE) risk, aortic stenosis and other cardiovascular diseases." (PMID 36230934, 2022).
hyperlipidemia (continued). "Conversely, PCSK9 has already been strongly linked to CVD, both from genetic and functional aspects, being a major target for control of hyperlipidemia and vascular disease in clinical practice, which therefore lowered its novelty for our study." (PMID 36188622, 2022). "Current commonly used medications for hyperlipidemia include, but are not limited to: statins that lower cholesterol synthesis; ezetimibe, which inhibits cholesterol absorption; and proprotein convertase subtilisin/kexin type 9, which lowers LDL receptors." (PMID 35565954, 2022). "We tested this notion using Fmr1−/− and Fmr1+/+ mice in which hyperlipidemia was induced by combining AAV_PCSK9 injection with a WD." (PMID 35191199, 2022). "Other medications used to treat hyperlipidemia include ezetimibe, fibrates, bile acid sequestrants, niacin, proprotein convertase subtilisin/kexin type 9 (PCSK9) inhibitors, and monoclonal antibodies." (PMID 35342693, 2022). "Endothelium-specific deletion of Txndc5 also markedly increased eNOS expression in the ligated LCA in Txndc5∆ECKO, compared with that in control (Cdh5-Cre/ERT2), mice with hyperlipidemia induced by PCSK9 overexpression and HFD." (PMID 35061532, 2022). "There are several medicines to control and manage hyperlipidemia, including proprotein convertase subtilisin/Kexin type 9 (PCSK9) inhibitors, statins, gemcabene, and ezetimibe." (PMID 35224859, 2022). "Although a longer-term study is yet to be initiated, the similarities in efficacy shared by alirocumab and NYX-PCSK9i in the same mouse model of hyperlipidemia add weight to NYX-PCSK9i′s viability as an alternative to monoclonal PCSK9 antibodies in the clinic." (PMID 36209894, 2022). "In conclusion, PCSK9 inhibition by alirocumab ameliorates systemic oxidative stress and hyperlipidemia in BDL-induced cirrhotic rats." (PMID 35806383, 2022). "In conclusion, PCSK9 inhibition by alirocumab treatment ameliorates hyperlipidemia and systemic oxidative stress in biliary cirrhotic rats." (PMID 35806383, 2022). "Inhibition of PCSK9 is a new therapeutic strategy for the control of hyperlipidemia, which can improve LDL-R circulation, increase the utilization of LDL-R on the surface of liver cells, and reduce the level of LDL-C in the blood." (PMID 36230934, 2022). "In this context, many clinical studies have clearly demonstrated the high efficacy of PCSK9 inhibitors in treating hyperlipidemia and cardiovascular diseases." (PMID 36552895, 2022). "Next, we induced hyperlipidemia in Fmr1−/− and Fmr1+/+ mice using a combination of AAV_PCSK9 injection and feeding with a WD." (PMID 35191199, 2022). "We assessed the potential of PCSK9 inhibitor-carrying RBCs as a long-term strategy to treat hyperlipidemia." (PMID 34731223, 2021). "Currently, anti-PCSK9 monoclonal antibodies have been clinically applied worldwide for the therapy of hyperlipidemia to decrease LDL receptor levels on liver tissue." (PMID 34504788, 2021). "In the process of hyperlipidemia, PCSK9 acts mainly through extracellular pathways, but in these experiments, we studied the role of PCSK9 in inhibiting the apoptosis of HCC cells through intracellular pathways." (PMID 33789749, 2021). "This is demonstrated by the success of genetic studies guiding the development of antibodies targeting PCSK9 (proprotein convertase subtilisin/kexin type 9) to treat hyperlipidemia and CVD." (PMID 33449144, 2021). "We found that a high level of PCSK9 expression is associated with poor prognosis in HCC, which coincides with the relationship between hyperlipidemia and HCC." (PMID 33789749, 2021). "As an alternative to mAbs, creating an immune response against PCSK9 through vaccination can be used to provide protection against hyperlipidaemia." (PMID 34356856, 2021). "The monoclonal antibodies against PCSK9 (alirocumab, evolocumab), which are used as a treatment for hyperlipidemia, lowered cholesterol levels and the incidence of cardiovascular diseases." (PMID 34071276, 2021).
hyperlipidemia (continued). "This preliminary study suggested the potential of using red blood cells genetically modified as circulating PCSK9 inhibitors to treat hyperlipidemia and obesity." (PMID 34731223, 2021). "Another approach to manage hyperlipidemia is through the release of proprotein convertase subtilisin/Kexin type 9 (PCSK9)." (PMID 34401212, 2021). "For example, inclisiran in LNP formulation as a small interfering RNAs (siRNA) against PCSK9 is used for a gene therapy of primary hyperlipidemias." (PMID 33639953, 2021). "Since its discovery in 2003 PCSK9 has emerged as an important target in the treatment of hyperlipidemia due to its role in hepatic LDL-clearance." (PMID 33169229, 2020). "In the past 10 years, with the emergence of related studies on PCSK9 inhibitors and other treatment of patients with statin-intolerant hyperlipidemia, including patients with FH, less attention has been paid to the analysis of PCSK9 variants than previously." (PMID 33173529, 2020). "Inclusion criteria included articles published in the last two decades (2000-2020), written in English, incorporated statin or PCSK9 inhibitors as therapy for hyperlipidemia, and compared these treatments to genders and or race." (PMID 33209524, 2020). "Insurance rejections, high copayments, physician perception of high risk, and African Americans’ lack of trust in the healthcare system all played a colossal part in the discrepancy in using statins or PCSK9 inhibitors to treat hyperlipidemia." (PMID 33209524, 2020). "This study will address the race and sex disparity in treating hyperlipidemia with statins versus PCSK9 inhibitors." (PMID 33209524, 2020). "For this study, we used the following keywords: statin therapy, PCSK9 inhibitors treatment of hyperlipidemia, race disparities, gender disparities, and healthcare disparities." (PMID 33209524, 2020). "The study indicated that Tanshinone IIA was able to regulate lipid metabolism by miR-33a/SREBP-2/Pcsk9 signaling pathway to reduce lipid deposition in the liver of hyperlipidemia rat." (PMID 32020855, 2020). "Together, these data suggest that miR-483 lowers circulating LDL-C levels by directly targeting the 3′-UTR of Pcsk9, which suggests the possibility for using miR-483 in treating hyperlipidemia." (PMID 33119548, 2020). "One of these intriguing new players in the field of hyperlipidemia therapy is monoclonal antibodies against proprotein convertase subtilisin/kexin type 9 (PCSK9)." (PMID 31191301, 2019). "This is exemplified by the recent success story of human genetic studies leading to rapid development of monoclonal antibodies targeting proprotein convertase subtilisin/kexin type 9 (PCSK9) for hyperlipidemia and cardiovascular disease." (PMID 31621579, 2019). "Proprotein convertase subtilisin/kexin type 9 (PCSK9) inhibitors, for example, represent a new therapeutic option that has recently entered the treatment landscape for patients with hyperlipidemia who are unable to achieve goal with statin monotherapy." (PMID 29273856, 2018). "Medical interventions targeting PCSK9 have emerged as a very promising therapeutic strategy in the management of hyperlipidemia." (PMID 30011788, 2018). "Assessment of the association between the DOCK7, PCSK9 and GALNT2 loci identified through GWAS 28, 29, 30 with the risk of hyperlipidaemia has become fundamental in the validation of these signals." (PMID 26493351, 2016). "miRNA-30c and miRNA-483 can also reduce hyperlipidemia by targeting Mtp and Pcsk9, respectively." (PMID 41398161, 2025). "PCSK9 monoclonal antibodies are one of the available options for the treatment of hyperlipidemia." (PMID 40478366, 2025). "Next, we assessed whether hepatic PCSK9 affects hyperlipidemia-induced expression of proinflammatory cytokines in mice liver." (PMID 39963241, 2025).
hyperlipidemia (continued). "Understanding the role of PCSK9 in this context could open new avenues for predicting and preventing hyperlipidemia in T2D patients, thereby improving clinical outcomes and reducing cardiovascular risk." (PMID 39951410, 2025). "Current research indicates that intestine-specific PCSK9 has less impact on lipidemia." (PMID 40732982, 2025). "In animal models of AAA induced by hyperlipidemia and angiotensin II, deletion or inhibition of PCSK9 has been found to significantly reduce the formation of AAA lesions, improve survival rates, and decrease systemic inflammation, independent of changes in circulating cholesterol levels." (PMID 40354375, 2025). "T2D patients with higher levels of PCSK9 in their blood are more likely to develop hyperlipidemia." (PMID 39951410, 2025). "Modulatory biomarkers such as proprotein convertase subtilisin/kexin type 9 (PCSK9), angiopoietin-like protein (ANGPTL), and fibroblast growth factors (FGFs) play a significant role in modulating the risk of hypothyroidism-associated hyperlipidemia." (PMID 39408957, 2024). "PCSK9 inhibitors are a novel group of medicines, recently approved for management of hyperlipidemia, particularly with those individuals in whom LDL target is not met despite maximally tolerated doses of statins, patients with FH, or those at high risk of cardiovascular events." (PMID 38919858, 2024). "Similarly, a comprehensive understanding of the epigenetic regulation of PCSK9 will help design potential therapeutic strategies to counter the adverse effects of statins in hyperlipidemia patients." (PMID 39566851, 2024). "Although PCSK9 inhibitors also have application value in the treatment of some tumors, viral infections, and other diseases, they are still mainly used in the treatment of hyperlipidemia, AS, and related ischemic cardiovascular diseases." (PMID 38344397, 2024). "Drugs targeting miR-181d-5p, an inhibitor of PCSK9, may therefore have broad application in the treatment of hyperlipidemia, viral infection, and cancer." (PMID 38940622, 2024). "For example, using the SNPs reported in seven studies as genetic instrumental variables, the risk of hyperlipidemia was augmented by increased APOB (OR = 3.28; 95% CI, 1.78–6.04; P = 1.44e-04), NCAN (OR = 1.41; 95% CI, 1.16–1.71; P = 4.73e-04), and PCSK9 (OR = 1.39; 95% CI, 1.25–1.54; P = 1.00e-09)." (PMID 39474612, 2024). "In response to this challenge, an inhibitor targeting proprotein convertase subtilisin-kexin type 9 (PCSK9) has been developed as a therapeutic intervention for hyperlipidemia, effectively achieving a significant reduction in low-density lipoprotein cholesterol (LDL-C) levels within a month." (PMID 39767636, 2024). "It was reported that inhibition of PCSK9 could be an effective method for reducing the unfavorable side effects of mTOR inhibitors-induced hyperlipidemia." (PMID 37896137, 2023). "In addition, mPEG‐b‐P(Met/n‐PMA)‐mediated PCSK9 gene editing has the potential to ameliorate hyperlipidemia." (PMID 37083231, 2023). "However, little is known about this specific mechanism, particularly how nutrition affects platelet activation and PCSK9 levels in hyperlipidemia conditions." (PMID 37892538, 2023). "Similarly, inclisiran is chemically synthesized against the PCSK9 protein related to hyperlipidemia, and the PD biomarker is the concentration of the PCSK9 protein." (PMID 36614189, 2023).